CD48 (CD48 molecule)
Diseases named in the same sentence as CD48 in open-access papers (continued):
Sharing a sentence is not in itself a finding about the gene and the disease.
infection (continued). "Cd48 expression increased 16-fold in liver after infection with T. congolense, but this occurred in all strains tested." (PMID 21085469, 2010). "The CD48+ CD150− CD135− MPP3 subpopulation is the one that is most strongly associated with monocyte and granulocyte fates both at steady state and under regenerative conditions, including during infection-adapted myelopoiesis." (PMID 35336108, 2022). "At the functional level, CD148+CD48+ MKs may benefit from their short distance to the blood vessel after infections and function as potential immune sensors and modulators, which may contribute to neutrophil migration and mobilization." (PMID 34042332, 2021). "Finally, the proportion of CD148+CD48+ MKs returned to the steady‐state level (i.e., prior to infection) 72 h after bacterial infection, when the platelet count also returned to normal." (PMID 34042332, 2021). "Indeed, we have reported that MCMV, which encodes the early m154 protein responsible for driving proteolytic degradation of CD48, can lead to defective NK cell responses during infection." (PMID 30947296, 2019). "At this time, both HSPCs (Lineage-, c-Kit+) and phenotypic long-term HSCs (Lineage- c-Kit+ CD135- CD150+ CD48) were depleted from the BM of WT mice during infection, but in Ifnar1-/- mice HSPCs were maintained and HSCs underwent a significant expansion as determined by both frequency and number." (PMID 30080899, 2018). "We hypothesize that CD48 participates in cell activation in response to infection and inflammation via interactions between CD48 and CD244 on mast cells, eosinophils, T-cells, and basophils." (PMID 30306094, 2018). "During infection, m154 leads to proteolytic degradation of CD48." (PMID 24626474, 2014). "We show that during infection, m154 targets CD48 for degradation." (PMID 24626474, 2014). "Moreover, we assessed whether this viral protein produced during infection was also capable to prevent the interaction of host CD48 with host 2B4." (PMID 30947296, 2019). "The PPI observed that the hub genes with the largest number of associated nodes in the weighted network played a crucial role in the immune cell recruitment and activation after infection, such CXCR1, VNN2, BST1, CREM, IL1R1, and CD48." (PMID 39692191, 2025). "We showed that the decreased engraftment potential of the LSK population on day 8 post-infection correlated with a decrease in the number of dormant HSCs, where dormant HSCs were characterized as LSK CD150+ CD48− CD135− CD34− cells." (PMID 22194881, 2011). "On day 8 post-infection the number of LSK CD150+ CD48− CD34+ CD135− cells was decreased, but the more differentiated LSK CD150+ CD48+ CD34+ CD135− and LSK CD150− CD48+ CD34+ CD135− cells increased in number." (PMID 22194881, 2011). "To determine the surface expression profiles of immune checkpoint ligands on DC subsets in the livers of mice at 24 weeks after infection, we further investigated the immune checkpoint ligands PD-L1, CD155, and CD48 and their expressions in the cDC and pDC subsets." (PMID 38787028, 2024). "It was previously shown that the viral mutant lacking m154 is attenuated early after infection in NK-dependent manner, attributing this phenotype to CD48, the first described target of m154." (PMID 31928630, 2020). "It was shown previously that MCMV lacking m154 is attenuated early after infection in NK-cell dependent manner, and this early attenuation was attributed to the subversion of CD48 signaling." (PMID 31928630, 2020). "However, no significant changes in the expression of CD48 in the cDC or pDC subsets after infection were observed." (PMID 38787028, 2024). "Therefore, each CMV might have evolved its own CD48-specific inhibitor, as yet to be identified for HCMV, emphasizing the importance of targeting this molecule to evade NK cell recognition during infection." (PMID 24626474, 2014).
infection (continued). "In the absence of an available blocking antibody to CD48, we examined whether incubation of the cells with heparan sulphate could inhibit B cell interaction with the epithelial cells, and thereby transfer infection." (PMID 21573183, 2011). "CD48 and NTB-A (the 2B4 and NTB-A cellular ligands, respectively) were not expressed on JEG-3 cells either prior to infection or following infection with PR8, or with BRI (data not shown)." (PMID 26919106, 2016). "After infection with the deletion mutant MCMV-GFPΔm144-m158 missing genes extending from m144 to m158, cell-surface CD48 was restored, reaching levels comparable to that of non-infected cells." (PMID 24626474, 2014). "The results showed no decrease in CD48, CD84, CD229, or Ly108 surface expression after infection of macrophages for 72 h with the UV-inactivated virus, indicating that SLAM downregulation could be attributed to specific MCMV genome-encoded products." (PMID 24626474, 2014).
bacterial infections (3 papers, 2018 to 2021). "Furthermore, CD48 was reported to be upregulated by viral-associated cytokines and bacterial infections and was shown to be involved in bacterial detection." (PMID 30306094, 2018). "We used a mouse model to analyze the change of CD148+CD48+ MKs upon bacterial infection." (PMID 34042332, 2021). "Notably, it has been shown that CD48 expression increases under inflammatory conditions such as during viral and bacterial infections, regulating target cell lysis and viral clearance mediated by cytotoxic cell lymphocytes." (PMID 32204481, 2020).
cardiovascular diseases (1 paper, 2025). "Literature review revealed that SELP and PECAM1 are associated with angiogenesis and cardiovascular diseases, while CXCR4, IL2RG, and CD48 are primarily involved in immune responses." (PMID 40612110, 2025).
inflammation (1 paper, 2018). Aberrant reaction of the microcirculation characterized by movement of fluid and leukocytes from the blood into extravascular tissues. "Thus, it is possible that CD48 is not systemically upregulated in allergic inflammation but only in tissues where the inflammatory reaction takes place." (PMID 30306094, 2018).
neurodegenerative disease (1 paper, 2023). A disorder of the central nervous system characterized by gradual and progressive loss of neural tissue and neurologic function. "In this study, CD48 and CD40 gene expression in AD, a neurodegenerative disease, was analyzed to infer this link." (PMID 36520044, 2023).
CD48 also shares sentences with these, for which no sentence is quoted: multiple myeloma (5 papers); primary Sjögren’s syndrome (3); lung carcinoma (2); lymphoid leukemia (2); metastatic melanoma (2); B-cell acute lymphoblastic leukaemia (1); bone marrow failure (1); Burkitt lymphoma (1); cervical cancer (1); chronic lymphocytic leukemia (1); Clear Cell Renal Cell Carcinoma (1); colitis (1); colorectal tumors (1); contact dermatitis (1); dilated cardiomyopathy (1); endometriosis (1); Epstein-Barr virus infection (1); experimental autoimmune encephalomyelitis (1); gastrointestinal disorders (1); Granuloma (1); Graves disease (1); heart failure (1); HIV-1 infection (1); IgA nephropathy (1); infectious disease (1); inflammatory skin disease (1); Iron deficiency anemia (1); latent infection (1); leprosy (1); lupus nephritis (1).
A further 12 diseases each share a sentence with CD48 in 1 paper.